ENSG00000286231 (novel protein)
Gene: Protein-coding gene on chromosome 1 (220,786,990 to 220,884,503, forward strand). Ensembl gene ENSG00000286231.
Genetic constraint (gnomAD): Missense variants: 384 observed, 367 expected, observed/expected ratio (o/e) 1.05, 90% interval 0.96 to 1.14. Synonymous variants: 159 observed, 149.6 expected, observed/expected ratio (o/e) 1.06, 90% interval 0.93 to 1.21.